FAT3 (FAT atypical cadherin 3)
Diseases named in the same sentence as FAT3 in open-access papers (continued):
Sharing a sentence is not in itself a finding about the gene and the disease.
cancer (41 papers, 2012 to 2025). A tumor composed of atypical neoplastic, often pleomorphic cells that invade other tissues. "Another group of cancer driver gene mutations commonly shared among OC patient samples was the family of FAT genes (FAT3 and FAT4)." (PMID 37446001, 2023). "Several of the genes, such as Mmp8, Dock10, Hoxd3 and Fat3, have previously been reported to show mutation or altered expression in cancer and particularly metastasis." (PMID 28577549, 2017). "FAT3 mutation is related to tumor mutation burden and poor prognosis in several cancers, which could also be related to the finding that the C1 subtype is associated with tumor metastatic potential and invasiveness." (PMID 36139456, 2022). "In human cancer, a point mutation in Fat3 results in pancreatic tumors." (PMID 34070222, 2021). "FAT3 and RELN, well-known tumor suppressors and mutated genes, are closely linked to poor prognosis in various cancer types, including TBNC." (PMID 39061186, 2024). "Further FAT3 mutations have been linked to prognosis and an elevated TMB level in multiple cancers, including NSCLC." (PMID 39727930, 2024). "For NECE, five genes were mutated in 80% of patients, including PIK3CA, FAT3, MUC2, PLEC, and TTN, among which PIK3CA and FAT3 belong to the COSMIC Cancer Gene Census gene tier 1 and 2, respectively." (PMID 37920164, 2023). "Gene enrichment analysis for KEGG revealed two pathways, the Hippo pathway, where DCHS2 was located, and the WNT/calcium pathway, where FAT3 was located, both of which are widely believed to be closely related to cancer." (PMID 37152984, 2023). "Differential gene expression analysis identified that inflammation‐responsive transcription factors, such as CCL3L1, characterized patients with relapse T‐ALL, along with deregulation of several key cancer regulators such as FAT3, CFTR and GLI3 (Figure SF1A)." (PMID 36819185, 2023). "FAT3 was relatively less studied and was thought to participate in the development of human cancer through a pathway similar to that of the Ena/VASP proteins." (PMID 33816234, 2021). "Compared with wild-type LUADs, patients in the FAT3+/LRP1B+ group were correlated with earlier cancer onset (median age 63.5 vs 67 years old, p=0.012), and the tumors were more commonly occurred in Black/African American (18.18% vs 8.30%, p=0.037)." (PMID 35069585, 2021). "Other cancer genes frequently altered in LC according to cBioPortal (e.g., ZFHX4, RYR2, CSMD3, FAT3, and RP1L1) were also found mutated at a high frequency in our cohort." (PMID 30925779, 2019). "The co‐occurred mutations in RNF43 and FAT3/FAT4 disrupted the Wnt signaling and thus promoted the development of cancer." (PMID 30107644, 2018). "Other members of FAT gene family, i.e., FAT1, FAT2 and FAT3, have been extensively characterized in various cancers recently." (PMID 26672766, 2016). "Expression levels of several previously reported genes implicated in cancer development and progression were altered, such as DDIT3, GATA6, UPP1, FAT3." (PMID 26158411, 2015).
cancer (continued). "Pan-cancer driver genes with high alteration rates include FLNA (Filamin A, 41.86%), MUC4 (Mucin 4, 41.86%), and FAT3 (FAT Atypical Cadherin 3, 39.53%)." (PMID 36653483, 2023). "FAT1, FAT3, and FAT4 are atypical cadherins and key regulators of cancer-relevant cellular processes including planar cell polarity and MST/HIPPO signaling, which regulates organ size." (PMID 33733072, 2021). "FAT3 and VCAN genes are intricately involved in processes such as cell adhesion, migration, and tumor invasion, all of which constitute pivotal aspects of cancer progression and metastasis." (PMID 38086955, 2023).
tumor (35 papers, 2009 to 2025). "Research has shown that TMB may be a potential marker for predicting the efficacy of immunotherapy, therefore, we explored the relationship between FAT3 mutation and tumor-infiltrating immune in ESCA." (PMID 33816234, 2021). "Furthermore, the GSEA of FAT3 mutation and the relationship between FAT3 mutation and tumor-infiltrating immune were explored." (PMID 33816234, 2021). "The human FAT1 and FAT3 gene encode large proteins with extracellular cadherin repeats that are associated with neurodevelopment and cell migration and are most homologous, which involved in tumor suppression." (PMID 32209061, 2020). "Briefly, knock-down of MEF2C-AS1 promoted aggressive tumor behaviors by reducing the protein levels of FAT3, NTN1, and LYVE1 which were related to proliferation and invasion in GC cell lines." (PMID 36064442, 2022). "The qRT-PCR results showed that the mRNA expression levels of FAT3, a putative tumor suppressor gene which codes for an atypical cadherin, were down-regulated in OV tissues." (PMID 35372348, 2022). "In order to better explore the mechanism of the mutant gene FAT3 in TNBC, we further explored the effect of FAT3 on tumor immune cell abundance and drug sensitivity." (PMID 33968045, 2021). "Of these, we found that heterozygous missense mutations in four genes—FAT4, FAT1, FAT3, and ERCC2—were predicted to be deleterious and also detected by tumor RNA sequence data, indicating that the mutant alleles were expressed in the tumor." (PMID 33733072, 2021). "FAT-family proteins, including FAT1, FAT3, and FAT4, were found to be expressed in all examined tumor samples, including those with mutations." (PMID 25743105, 2015). "Other regulated signalling molecules included guanine exchange factors that play a role in an activation of the MAP kinases while several tumor suppressors i.e. Mcc, Hey1, Fat3, Armcx1 and Reck were significantly repressed." (PMID 19812696, 2009). "This hypothesis was supported by our snRNA-seq analysis, in which we clearly observed that genes related to neuronal migration and axon guidance (CNTN1, PTPRG, NTRK2, FAT3, etc.)were more upregulated in neuron cell clusters than in tumor cell clusters." (PMID 38609519, 2024). "However, the FAT family genes, including FAT3, has been described to be involved in tumor suppression." (PMID 35078526, 2022). "FAT3 belongs to a family of proteins that includes two known tumor suppressors, FAT1 and FAT4." (PMID 35282432, 2022). "FAT3 belongs to the FAT family genes encoding large proteins with extracellular Cadherin repeats, EGF-like domains, and Laminin G-like domains, and is involved in tumor suppression and planar cell polarity (PCP)." (PMID 35069585, 2021). "The simultaneous prominence of the three types cells, CD8+ T cells, activated CD4+ memory T cells and M1 macrophages, implying that co-mutation of FAT3 and LRP1B can be used to predict the cytotoxic effect of lymphocytes against tumor cells and the beneficial response of immunotherapy in LUAD." (PMID 35069585, 2021). "We found that co-mutation of FAT3 and LRP1B has prominent significance, which can increase somatic mutational load, boost cytotoxicity and tumor immunogenicity, facilitate lymphocyte infiltration in the microenvironment, and significantly influence the outcome of immunotherapy." (PMID 35069585, 2021). "FAT3 is also a member of the FAT family involved in tumour suppression." (PMID 34085405, 2021).
tumor (continued). "Additionally, among the top 20 mutated oncogenic genes in the low-DR group, we identified mutations that closely correlated with tumour progression, such as those in APC and FAT3,71,72 indicating a more malignant characteristic of the tumours in low-DR patients." (PMID 38507875, 2024). "It was thus possible to identify genes (CNTN1, FAT3, EPHA3, EPHA5, NLGN1, etc.)that contribute to PC2 and are differentially expressed in radial glial cells between normal and tumor samples." (PMID 38609519, 2024). "In addition, in the FAT3 mutation group, a correlation was found between the abundance of various immune cells and TMB level, TMB and immune cell infiltration are closely related to the pathological activities of tumor cells and are related to the prognosis of patients." (PMID 33968045, 2021). "Nevertheless, our germline analysis identified four genes with known functions likely to contribute to tumor progression and potentially drug response: FAT1 and FAT3, FAT4, and ERCC2, modeled by targeting kug, ft, and xpd, respectively." (PMID 33733072, 2021). "FAT1, FAT2, FAT3 and FAT4 are human homologs of Drosophila Fat, which is involved in tumor suppression and planar cell polarity (PCP)." (PMID 23076869, 2012). "We observed genetic heterogeneity also in spheroids for several genes, as indicated by low SNV frequencies, for instance, in ADAMTS7, CSMD3, ERN1, FAT3, and RAD51C/D, supporting the view that tumor lesions are composed of mixed tumor cell populations with varying frequencies of SNVs." (PMID 32533757, 2020). "As a result, we observed that neuron-related genes (CNTN1, FAT3, PTPRG, NTRK2, etc.)annotated to categories such as nervous system development, neuron differentiation, generation of neurons, and neurogenesis were downregulated in tumor cluster cells (Online Resource)." (PMID 38609519, 2024).
infection (4 papers, 2008 to 2025). The state of being infected such as from the introduction of a foreign agent such as serum, vaccine, antigenic substance or organism. "We demonstrate that this reduction in basal activity of p38 MAP kinase signaling and the concomitant increased susceptibility to both infection and oxidative stress, due to loss of fat-3 function, are associated with GLA and SDA deficiencies." (PMID 19023415, 2008). "Interestingly, each of the 16 fat-6-dependent, fat-3-independent genes encode putative immune effectors that are induced during infection with at least one bacterial pathogen, a group that includes the innate immune effectors irg-4, irg-5, and irg-6." (PMID 31206555, 2019). "Nandakumar and Tan found that fat-3 regulates the expression of stress response and infection genes, involved in immune function and oxidative stress response." (PMID 37672050, 2023). "We have provided several lines of evidence that the decreased ability of fat-3 mutants to survive infection by P. aeruginosa is a consequence of diminished synthesis of GLA and SDA." (PMID 19023415, 2008). "Expression of fat-3 in neuronal tissues was similarly ineffective at restoring infection-response gene expression; expression of only two genes, F35E12.8, and F08G5.6 were restored to wild-type." (PMID 19023415, 2008). "Given that fat-3 expression in the intestine is required to protect C. elegans from P. aeruginosa-mediated killing, we wondered if expressing fat-3 in the intestine would be sufficient to restore the expression of infection-response genes in the fat-3 mutants." (PMID 19023415, 2008). "To provide a further link between fat-3 gene function and innate immunity, we compared the expression of 50 infection-response genes by qRT-PCR, in 1-day-old adult wild-type and fat-3(wa22) animals." (PMID 19023415, 2008). "Analysis of tissue-specific fat-3 gene expression on infection survival, defecation and locomotion." (PMID 19023415, 2008). "Transcriptional and functional analyses of fat-3–regulated genes revealed that fat-3 is required in the intestine to regulate the expression of infection- and stress-response genes, and that distinct sets of genes are specifically required for immune function and oxidative stress response." (PMID 19023415, 2008). "Together, these data confirm our hypothesis that fat-3 functions in the intestine to influence the expression of a number of infection-response genes that contribute to the protecting C. elegans from P. aeruginosa infection." (PMID 19023415, 2008). "Here, with the fat-3 mutant, we demonstrate the essential requirement of a constitutive immune response pathway for survival against the pathogen, despite the presence of a functional inducible infection response in C. elegans." (PMID 19023415, 2008). "Additionally, genes related to cell adhesion such as ADGRF5, CAVIN2, FAT3, FILIP1, GSN, and TSPAN11 were downregulated in both the variants at 24hpi whereas CAV1, CAVIN1, GPC3, POSTN, SUSD2, and TSPAN7 were downregulated only after Delta variant infection at 24 hpi." (PMID 41200555, 2025). "Intestine-specific expression of fat-3 restored the expression of seven of the eight the down-regulated infection-response genes, including the immune-specific genes spp-1, lys-7 and F08G5.6, indicating that fat-3 is required in the intestine to regulate basal gene expression." (PMID 19023415, 2008). "Despite retaining an intact response to infection in the absence of GLA and SDA, reduction in basal p38 MAP kinase signaling in the fat-3 mutant was sufficient to cause increased susceptibility to both infection and oxidative stress, highlighting the vital importance of basal immunity." (PMID 19023415, 2008).
bacterial infection (2 papers, 2008 to 2019). "Intestine-specific rescue of fat-3 pathogen sensitivity indicates that fat-3-dependent synthesis of PUFAs in the intestine is sufficient for normal immune function in response to bacterial infection." (PMID 19023415, 2008). "Also of note, the effect of fat-3(wa22) on susceptibility to bacterial infection was independent of oleate." (PMID 31206555, 2019).
FAT3 also shares sentences with these, for which no sentence is quoted: colon cancer (2 papers); esophageal cancer (2); adenocarcinoma (1); adolescent idiopathic scoliosis (1); Alzheimer disease (1); autism (1); autism spectrum disorder (1); bladder cancer (1); breast adenocarcinoma (1); diabetes (1); gastric cancer (1); glioma (1); head and neck squamous cell carcinoma (1); hearing loss (1); hepatocellular carcinoma (1); heroin addiction (1); Hirschsprung disease (1); hyperlipidemia (1); Mcc (1); meningioma (1); microcephaly (1); neurodevelopmental disorder (1); Obesity (1); oesophageal cancer (1); ovarian serous cystadenocarcinoma (1); pancreatic acinar cell carcinoma (1); pancreatic ductal adenocarcinoma (1); periodontitis (1); rectal cancer (1); rectal NETs (1).
A further 4 diseases each share a sentence with FAT3 in 1 paper.